SRC (SRC proto-oncogene, non-receptor tyrosine kinase)
Diseases named in the same sentence as SRC in open-access papers (continued):
Sharing a sentence is not in itself a finding about the gene and the disease.
schwannoma (1 paper, 2017). A benign, usually encapsulated slow growing tumor composed of Schwann cells. "Analysis of phospho-receptor tyrosine kinase and phospho-kinases proteome profiler arrays revealed that schwannomas consistently had higher levels of phosphorylated PDGFRα, PDGFRβ, SRC, MEK and STAT3 compared with control primary HSC." (PMID 28427224, 2017). "Lastly, primary human schwannoma cells treated with the SRC inhibitor SU6656 exhibit decreased transcription of proliferation-associated genes." (PMID 28427224, 2017). "In human schwannoma cells, SRC activity is increased compared to normal Schwann cells, and in mouse glia cells, merlin inhibits proliferation by modulating SRC activity." (PMID 28427224, 2017). "To assess activation of PDGFRα/β and SRC in human schwannomas, we surveyed a phospho-proteome profile comparing five human vestibular schwannoma specimens with primary normal adult human Schwann cells cultured in the presence of mitogens to stimulate their proliferation." (PMID 28427224, 2017). "Schwannomas exhibited averaged 6.6 times higher PDGFRα phosphorylation, 5.4 times higher PDGFRβ phosphorylation, 30 times higher SRC phosphorylation, 5.6 times higher MEK phosphorylation and 7.4 times higher STAT3 phosphorylation compared with control primary HSC." (PMID 28427224, 2017). "Following merlin depletion, HSC increased the levels of phosphorylated SRC and PDGFRα/β, in agreement with studies in primary human NF2 schwannoma cells." (PMID 28427224, 2017). "It would be interesting to investigate if other SRC inhibitors, including SU6656, that have anti-proliferative activity in primary human schwannoma cells, also increase SRC levels." (PMID 28427224, 2017).
scleroderma (1 paper, 2022). Scleroderma is a rare autoimmune connective tissue disorder characterized by abnormal hardening of the skin and, sometimes, other organs. "A link between ROS and SRC signaling in scleroderma fibroblasts was previously reported." (PMID 35451370, 2022). "Here, we assessed whether oxidation of PTP4A1 modulates its profibrotic action and found that PTP4A1 forms a complex with the kinase SRC in scleroderma fibroblasts, but surprisingly, oxidative stress enhanced rather than reduced PTP4A1’s association with SRC and its profibrotic action." (PMID 35451370, 2022).
serous ovarian cancer (1 paper, 2022). "In high‐grade serous ovarian cancer (HGSOC), combination of MEK (AZD6244) and SRC (saracatinib) inhibitors overcomes EGFR‐mediated bypass of the RAS‐MAPK pathway and targets tumour initiating stem cells." (PMID 34856074, 2022).
small intestinal NETs (1 paper, 2021). "An increase in SRC copy number correlated with decreased patient survival in a small set of small intestinal NETs, and SRC mRNA was increased in samples with elevated SRC copy number." (PMID 34680217, 2021).
thymoma (1 paper, 2024). A neoplasm arising from the epithelial cells of the thymus. "Our research screened out the core target genes AKT1, MMP9, STAT3, SRC, and EGFR of thymoma-associated M, and carried out molecular docking verification." (PMID 37498332, 2024).
typhoid fever (1 paper, 2012). A bacterial infectious disorder contracted by consumption of food or drink contaminated with Salmonella typhi. "Most recently, another murine lethal S. Typhi model resembling characteristic features of human typhoid fever was created by making use of humanized nonobese diabetic-scid IL2rγnull mice, which are engrafted with human hematopoetic stem cells (hu-SRC-SCID mice)." (PMID 23055923, 2012).
urothelial carcinoma (1 paper, 2019). A malignant neoplasm derived from the transitional epithelium of the urinary tract (urinary bladder, ureter, urethra, or renal pelvis). "Immunohistochemical analysis revealed that p-c-SRC expression co-expressed with pSMAD2C in all of the histo-subtypes tested including papillary, urothelial carcinoma with squamous differentiation and sarcomatoid." (PMID 31554791, 2019). "Furthermore, p-c-SRC expression correlated with nuclear pSMAD2C in 2/2 papillary urothelial carcinoma and 5/6 urothelial carcinoma with squamous differentiation bladder carcinoma and neuro-endocrine bladder carcinoma." (PMID 31554791, 2019).
wasting syndrome (1 paper, 2018). "Further studies will clarify the relation of cPLA2α/AA/SRC, CYP1A1, and Tiparp pathways in TCDD-induced weight loss or wasting syndrome." (PMID 29043426, 2018).
cancer (673 papers, 1991 to 2026). A tumor composed of atypical neoplastic, often pleomorphic cells that invade other tissues. "Variants in the APCDD1, CYBA, PTK7 and SRC genes were identified in more than one family, and they were shown to dysregulate basic cellular functions, potentially leading to cancer development." (PMID 41469725, 2025). "The efficacy of SRC inhibitors and autophagy inducers in treating cancers with loss of BAP1 was further validated through the use of patient-derived tumor organoids (PDTOs) as preclinical models." (PMID 40754831, 2025). "Significance: Deadly cancers with BAP1 mutations suppress autophagy by phosphorylating the autophagy regulator BECN1 via the proto-oncogene SRC." (PMID 40754831, 2025). "SRC is overexpressed or mutated in many cancers and contributes to tumor initiation, invasion, angiogenesis, and metastasis." (PMID 41439111, 2025). "RNA-seq and downstream analyses revealed that increased cytMaspin expression downregulated the genes associated with cell adhesion and activated PYK2 and SRC, which play important roles in cancer progression." (PMID 39272867, 2024). "The third significant protein of interest is SRC, one of the nine members of the Src family of tyrosine kinases (SFKs), which is implicated in the development and progression of multiple cancer types." (PMID 39720087, 2024). "Collectively, our study demonstrates that cGAS antitumor signaling is hindered by the proto-oncogene SRC and describes how cancer-associated proteins can regulate the innate immune system." (PMID 37166992, 2023). "The SRC gain- and loss-of-function (GOF and LOF) assays demonstrated that SRC kinase regulated the cancer stemness and metastasis of TNBC cells in vitro and in vivo." (PMID 36633714, 2023). "In line with our findings, SRC-mediated YAP1 activation through direct phosphorylation has been implicated in many cancer progressions and tumor microenvironment regulation." (PMID 36633714, 2023). "The elevated activities of SRC are associated with the development and progression of a number of cancers by promoting oncogenic signals." (PMID 37046850, 2023). "According to the COSMIC database, SRC is overexpressed in various human cancers; however, mutations in SRC are rare." (PMID 37439249, 2023). "While SRC is rarely mutated in cancer, it often functions downstream of oncogenic drivers in signalling cascades including those initiated by receptor tyrosine kinases (RTKs) and at integrin‐linked focal adhesions." (PMID 34856074, 2022). "A key regulator of cell-matrix and cell-cell adhesions, SRC has been implicated in a number of cancer-associated phenotypes, including proliferation, migration and invasion." (PMID 36016606, 2022). "SRC is known to play critical roles in regulating biological functions associated with cancer progression such as cell proliferation, differentiation, cellular migration and angiogenesis." (PMID 35273218, 2022). "Among these members, SRC is the first ever described tyrosine kinase proto-oncogene and also the most frequently implicated in tumorigenesis and metastasis of various cancer types, especially for BC." (PMID 36581908, 2022). "With few exceptions, increased SRC activity is generally associated with late-stage cancers, metastatic potential, and resistance to therapies, and correlates with poor clinical prognosis." (PMID 34417202, 2021). "By performing WGS and integrative in silico analysis on a CRC-affected family using our FCVPPv2, we were able to identify a novel germline variant in SRC gene (V177M) contributing to cancer predisposition." (PMID 33916261, 2021). "Induction of signaling pathways such as STAT3 or PI3K pathway via up-regulation of SRC signaling has been linked to cancer progression." (PMID 34399705, 2021). "The expression and activity of SRC are associated with advanced malignancy and poor prognosis in a variety of human cancers." (PMID 34335829, 2021).
cancer (continued). "The SRC oncogene has been strongly implicated in the initiation and progression of various human cancers." (PMID 34862372, 2021). "Alternative splicing of cancer-associated genes such as fibroblast growth factor and insulin receptors, signaling kinases such as SRC and RAS, or the BRCA1 tumor suppressor have been reported from hnRNPA1-deregulated cells." (PMID 32417965, 2020). "It is also interesting that the SRC-induced TGFβ pathway activation via α-SMA is associated with the promotion of cancer-associated fibroblasts (CAFs), which further increase chemotactic mediated migration of GBM cells." (PMID 33020459, 2020). "Aberrant SRC expression is detected in most GCs and is also associated with cancer progression and poor prognosis, providing a clinical rationale for the use of SFK inhibitors as effective targeted therapy for the treatment of GC." (PMID 33291786, 2020). "For further verification of the role of SRC in the miR-654-3p-associated anti-cancer mechanism, a rescue experiment of SRC was evaluated by upregulating miR-654-3p and SRC at the same time in HCT116 and SW480, respectively." (PMID 33193697, 2020). "Phosphorylation of FAK in cancer cells is associated with integrin adhesion dynamics and deregulation of E-cadherin during SRC associated epithelial to mesenchymal transitions." (PMID 31781558, 2019). "These cancer activities are linked to SRC’s capacity to promote CRC cells invasion and CSC activity." (PMID 31091767, 2019). "While the overexpression/hyperactivation of SRC is associated with poor prognosis in patients suffering from various cancers, similar studies for LYN and FYN led to varied conclusions." (PMID 29937990, 2018). "The first virus ever identified to cause cancer encoded a viral isoform of c-SRC (also known as pp60src)." (PMID 28513565, 2017). "SRC plays a major role in different aspects of oncogenesis and was described to be mutated in various human cancers." (PMID 28146430, 2017). "For example, mutations in genes such as PTEN, SMAD2, TGFB2, and SRC implicated in epithelial-mesenchymal transition, metastasis, and cancer progression, were enriched in more aggressive groups while the other genes clustered in the less aggressive groups." (PMID 28007036, 2016). "In conclusion, we show that fibroblasts induce cell-contact-dependent CRC cell migration and invasion under 2D and 3D conditions in vitro through surface associated FGF-2, FGFR-mediated activation of the SRC in cancer cells and αvβ5-mediated adhesion." (PMID 25973543, 2015). "Activated SRC phosphorylates a diverse spectrum of substrates that results in up-regulation of several cancer-associated pathways including EGFR signaling." (PMID 25301722, 2014). "Here, we identified an autophagic vulnerability in cancers with BAP1 mutations involving the oncogenic tyrosine kinase SRC and the autophagy protein BECN1 that can be therapeutically targeted, opening the possibility of novel treatments specific for tumors with BAP1 loss." (PMID 40754831, 2025). "The SRC gene is associated with cancer cell migration and invasion." (PMID 40699827, 2025). "Additionally, the overexpression of SRC and its associated substrates underscores their involvement in cancer cell motility, invasiveness, and lymph node metastasis, implicating them as crucial players in OSCC progression and spread." (PMID 37623256, 2023). "SRC, the protein tyrosine kinase, is associated with cancer and OP39." (PMID 38155235, 2023). "Notably, accumulating evidence has linked deregulated SRC activity or expression levels to malignant progression, cancer stemness, and chemoresistance in CRC." (PMID 37760971, 2023). "Therefore, YAP1 tyrosine phosphorylation represents a potential mechanism for SRC activation-associated human cancers." (PMID 36633714, 2023).
cancer (continued). "Interestingly, compared to FAT1 wild‐type cancer cells, the loss of FAT1 dramatically enhances the drug sensitivity of cancer cells to dasatinib, saracatinib (SRC inhibitors), and KN93 (CAMK2 inhibitor)." (PMID 35601657, 2022). "Even though post-translational modifications of the SRC protein have been widely studied as the underlying cause of high SRC activity in cancer, less is known about activating variation of the SRC gene in human CRC besides the somatic truncating mutation SRC531." (PMID 33916261, 2021). "Although SRC is rarely mutated in human cancers, its activity is frequently elevated." (PMID 30559289, 2019). "In addition, many of the same cancer-associated microenvironmental cues and oncogenic events that regulate SRC also influence YAP and TAZ." (PMID 30559289, 2019). "SRC, encoding a tyrosine kinase receptor, is frequently implicated in cancer." (PMID 30809968, 2019). "Furthermore, the p.Trp257Gly mutation has also been shown to increase cancer cell migration through the SRC-JNK-c-Jun pathway." (PMID 29682207, 2018). "This indirectly suggested that SRC overexpression might act as an essential compensatory mechanism for the loss of EPHB6 in cancer cells, indicating that the SL interaction of EPHB6 and SRC may represent a promising therapeutic target." (PMID 27418135, 2016). "Moreover, we further verified whether tricin critically influenced the key target SRC during cancer cell growth and probed the underlying mechanism by overexpressing SRC in H358, H2122 and LLC cells via stable transfection." (PMID 40599804, 2025). "Moreover, the signaling mechanisms implicated in SRC could potentially impact the proliferation, survival, migration, and invasion of cancer cells." (PMID 41325388, 2025). "Therefore, the TSE-mediated activation of the SRC-FAK circuit might promote EMT-associated cancer cell migration and invasion." (PMID 37439249, 2023). "The establishment of several key principles in cancer biology is also owed in part to the study of tumor viruses, including the discovery of cancer-driving ‘oncogenes’ identified through studies of the avian onco-retrovirus Rous Sarcoma Virus that encodes the SRC oncogene." (PMID 36298759, 2022). "SRC is implicated in cellular adhesion, invasion, proliferation and mutagenesis as well as the regulation of angiogenesis and bone remodelling leading to metastasis, which together represent four of the six hallmarks of cancer as defined by Hanahan and Weinberg." (PMID 32082487, 2020). "In addition, we identified three heterozygous candidate missense variants in known cancer susceptibility genes (BMPR1A,BRIP1, and SRC), three truncating variants in possibly novel cancer genes (CLSPN,SEC24B, SSH2) and four candidate missense variants in ACACA, NR2C2, INPP4A, and DIDO1." (PMID 30809968, 2019). "ROS promote anoikis resistance in cancer cells by activating survival pathways like SRC-EGFR signaling, which sustains metabolic adaptation and prevents apoptosis during matrix detachment." (PMID 41596231, 2026). "EXOSC5 upregulates NTN4 expression, activating c-MYC through the integrin β1/FAK/SRC pathway to sustain cancer stem cell activity." (PMID 41235257, 2025). "The positive correlations between the expression of PINK1, SRC, BECN1, and OPTN and drug sensitivity suggest that higher levels of these genes are associated with increased vulnerability of cancer cells to treatment." (PMID 39859167, 2025). "The MBD Try1349 and 1356 provide a docking platform to recruit the Src homology-2 domain, phosphotyrosine-binding domain, and other critical MBD adapter proteins GAB1, GRB2, phospholipase C, and SRC required for activating cancer motility." (PMID 41470892, 2025). "CD318 is known to be involved in the SRC activation pathway, thereby modulating cell growth, survival, and metastasis in cancer." (PMID 40725832, 2025).